RNU6-135P (RNA, U6 small nuclear 135, pseudogene)
Gene: Small nuclear RNA gene on chromosome 1 (23,163,953 to 23,164,053, forward strand). Ensembl gene ENSG00000252578.
Homologues: Orthologues: chimpanzee U6 (99% identical), macaque U6 (84% identical), guinea pig U6 (40% identical). Paralogues in human: RNU6-1024P (75% identical), RNU6-15P (75% identical), RNU6-34P (75% identical), RNU6-86P (75% identical), RNU6-1 (74% identical), RNU6-1060P (74% identical), RNU6-116P (74% identical), RNU6-11P (74% identical), RNU6-1263P (74% identical), RNU6-19P (74% identical), RNU6-2 (74% identical), RNU6-21P (74% identical), and 1287 more.